IRF7 (interferon regulatory factor 7)
Diseases named in the same sentence as IRF7 in open-access papers (continued):
Sharing a sentence is not in itself a finding about the gene and the disease.
infection (continued). "qPCR analysis of Irf7 expression in the ileum and jejunum of Mettl3ΔIEC mice and littermate controls was carried out at 2 days post infection (dpi) (littermate WT n = 4, Mettl3ΔIEC mice n = 3, mean ± SEM)." (PMID 35098923, 2022). "Our results showed that the expression levels of TLR3, IFIH1, and IRF7 were increased after infection in resistant chickens; and expression levels of IRF7 were higher in resistant H5N1-infected chickens than in susceptible H5N1-infected Ri chickens." (PMID 34991196, 2022). "In primary swine macrophage cultures, infection with VSV 1.1 downregulated the transcription of interferon regulatory factor 7 (IRF-7)." (PMID 35746691, 2022). "Administering liposomal IRF-7 siRNA to IRF-3 knockout mice suppressed mucosal IRF-7 expression, and the mice were protected against infection and renal tissue damage." (PMID 35860746, 2022). "When performing an analysis focusing on inflammation and infection associated factors in IPA, we found a strong Z-score for IFNβ, IFNA2, IRF1, and IRF7 signaling." (PMID 36032117, 2022). "Of note, for VSV-GFP infection, impaired IRF7 expression correlated with enhanced GFP protein expression, indicating increased VSV replication." (PMID 35013241, 2022). "Our analyses indicated that despite the presence of baseline inflammation, 2 yr old mice had significantly lower induction of innate immune genes at 2 days post-infection, including Il6, Ccl4, Cxcl10, Rig-I, Irf7, Ifna2, Oas1b, and Mx2." (PMID 36679892, 2022). "The irf7 predicted to be targeted by nbr-miR-731 was also higher expressed in the spleen of fish at 6 h after infection, but then its expression dropped gradually to a lower level at 16 h." (PMID 36059498, 2022). "Upregulation of many genes associated with activation of innate immunity and SARS CoV-2 disease severity were identified during acute (4 dpi) SARS-CoV-2 (Delta variant) infection in cats, such as KIF11, IRF7, OAS1, BATF2, IF16, and BPIFA1." (PMID 35746678, 2022). "Based on the transcriptional network analysis, we found that IRF7 is similarly positioned in the hub of the IFN response after infections by HSV and CMV." (PMID 34389779, 2021). "Of note, the levels of phosphorylation of IRF3 and IRF7 in U937 cells infected with m6A-deficient HIV-1 were 2.6- and 3.1-fold higher than those in mock infection, and 1.6- to 1.7-fold higher compared to cells infected with control HIV-1." (PMID 33690734, 2021). "There was higher expression of IFN-β, IFIT1, IFIT3, ISG15, and IRF7 mRNA in A549 XRN1 KO cells after 8 h of infection with various virus strains, including WSN (H1N1), PR8 (H1N1), CA04 (H1N1), and HK4801 (H3N2)." (PMID 34311580, 2021). "To further investigate the innate immunity pathways regulated by DDX5, we detected the expression of p-TBK1, p-IKKγ, p-p65, and p-IRF7 in DDX5- or METTL3-knockdown or -overexpressing MEFs after infection with VSV." (PMID 33909701, 2021). "Irf1, Irf7, Irf8, and Irf9 transcripts were significantly induced by infection in Ifnar1-/- mice, whereas Irf6 transcripts (abundant in uninfected mice) were significantly down-regulated." (PMID 34591933, 2021). "In accordance with this, our results showed that TLR3, RIG-1, MDA-5, and IRF7 were activated during GNAstV infection." (PMID 33647718, 2021). "After STM infection migratory ILCs express significantly higher levels of Ccl3, Gbp2, Gbp6, Irf1, Irf4, Irf7, Pml and Stat1, all of which are regulated in response to interferon gamma." (PMID 33414524, 2021). "When we looked at different IRFs, we found that Irf7, Irf8, Irf5, and Irf4 were significantly upregulated in WT mouse brains upon infection with JEV." (PMID 34379515, 2021). "For infections by HSV-1, dengue virus, and lymphocytic choriomeningitis virus, IRF7 plays a critical role in viral protection as was shown in IRF7-deficient mice." (PMID 34389779, 2021).
infection (continued). "Most of the well-studied ISGs—such as Protein Kinase R (PKR), 2’-5’-Oligoadenylate Synthetase 1 (OAS1), IRF7, and RNAseL—require activation by infection-dependent signals, whereas select other ISGs—such as IRF1—are synthesized in a constitutively active form." (PMID 33808506, 2021). "The genes Mx2, Irf7, Ddx58 and Stat1gene transcripts were found up-regulated early in the infection (2 and 4 dpi), whereas Ccl5 was up-regulated only at 4 dpi." (PMID 33941622, 2021). "As for the two tested DNA viruses, HSV-1 was less affected by overexpression of the IRFs; only IRF1 and IRF7 decreased replication at 48 h post infection, with IRF7 catching up with the empty vector controls 56 h post infection." (PMID 34685580, 2021). "Our transcriptomic data also showed that IFR7 was firstly induced by DTMUV infection, followed by a significant induction of IFNα/β in a later time point, supporting the regulatory role of IRF7-induced IFNα/β expression in DTMUV infection." (PMID 32983049, 2020). "This indicates the critical role that IRF3 and IRF7 play in not only activating the type I IFN response at early stages of infection, but also in controlling these IFN levels to prevent neurotoxicity." (PMID 32708188, 2020). "By binding to viral RNA, OASL1 supports MDA5-mediated IFN production early in infection, while its binding to IRF7 mRNA prevents IRF7 synthesis and thereby dampens transcriptional activation of IFN at later time points." (PMID 32899736, 2020). "The level of IRF7 mRNA in the livers of rhesus macaques was increased at the peak of HEV1-Sar55 infection, but was reduced when the same monkeys were re-infected." (PMID 32731452, 2020). "When type I IFN levels were assessed in IRF3 or IRF7 knockout mouse models at later stages of infection (5 days post infection), significantly higher levels of IFN were produced compared to wild type." (PMID 32708188, 2020). "This is consistent with the observation that Irf3−/− mice demonstrated a more severe decrease in early liver ISG induction compared to Irf7−/− mice following P. berghei (ANKA) infection." (PMID 33408718, 2020). "This shifts the control of gene expression in fibroblasts, epithelial and endothelial cells from IRF3-mediated regulation upon initial sensing of an infection towards IRF7-mediated in later phases." (PMID 32645843, 2020). "For instance, we observed differential expression of genes that are involved in the membrane trafficking pathways, such as endocytosis, lysosomes and phagosomes, as a result of IRF7 KO after infection, as well as at baseline." (PMID 32252379, 2020). "A minimal increase in mycobacterial burden was detected in Mavs–/–BMMs as well as RIG-I, TBK1, IRF3 or IRF7-knockdown BMMs when compared to WT or control siRNA-treated cells at 72 hr post infection." (PMID 32463840, 2020). "Histological analyses of virus-infected cells in the olfactory bulb revealed that the virus was cleared in wildtype mice, whereas infected cells were still detectable in Irf-7−/− mice 16 days post-infection." (PMID 32951602, 2020). "Our previous work has identified candidate genes that were regulated by IRF7 in the context of H6N2 infection by applying an inducible overexpression-based gain-of-function approach." (PMID 32252379, 2020). "Upon infection, there were 138 down- and 100 up-regulated DEGs at 2 hpi due to IRF7 deletion, and the number of DEGs increased to 441 down- and 483 up-regulated genes at 6 hpi." (PMID 32252379, 2020). "The early phosphorylation of IRF3 and IRF7 was particularly triggered by infection with the pde2 mutant, implicating this pathway in the select responses of macrophages to these Δpde2 bacteria." (PMID 32300347, 2020). "In P1, six of eight cell types studied demonstrated higher expression of IRF7 at peak viremia compared to pre-infection and 1-year timepoints." (PMID 32251406, 2020).
infection (continued). "Here, we identified that re-infection of IRF7-/- mice (at 7 weeks of age) induces an increase in ASM area, and that this phenotype persists for at least 8 weeks." (PMID 32658914, 2020). "For the distantly related arboviruses Dengue (DENV) and Chikungunya (CHIKV) virus it was recently shown that pDCs are sufficient to control these viruses via IRF7-regulated type I IFN responses in both systemic as well as local infection settings." (PMID 31031767, 2019). "This included IFITM1 and IFITM2, which are known to inhibit the infection and replication of respiratory syncytial virus, IFI27, a known biomarker for RSV29, and IRF7, a gene associated with suppression of innate immunity response." (PMID 31554845, 2019). "Both CuO-IRF7 and control cell lines were induced with 0, 20, or 40 μg/ml of cumate for 24 h which correspond to approximately 10, 50, and 100-fold overexpression of IRF7 in CuO-IRF7 cells compared to the control cells at the time of infection." (PMID 30356848, 2018). "In our study, Tyrosine kinase 2 (TYK2, one of the JAKs) and its negative regulators SOCS1, SOCS3 as well as anti-apoptosis genes BCL-XL and PIM1 were differentially regulated by IRF7 during the H6N2 infection." (PMID 30356848, 2018). "Each condition had 2 independent biological replicates and principal component analysis showed that the replicates in each condition grouped together by either IRF7 expression level or H6N2 infection condition." (PMID 30356848, 2018). "Our studies suggest that in dDCs, IRF7 is primarily activated following infection with CCHFV, whereas in LCs, IRF1 activation is primarily increased." (PMID 30036960, 2018). "Then, we further analyzed the interaction of IRF7 overexpression by H6N2 infection to identify the genes that were differentially regulated during the infection by IRF7." (PMID 30356848, 2018). "Irf3 mRNA expression was decreased in microglia following infection and remained unchanged in astrocytes, contrasting with upregulation of Irf7 mRNA in both cell types between days 3 to 5 p.i. and downregulation thereafter." (PMID 29491163, 2018). "In the case of IPNV aborted infection in rainbow trout RBCs, there was an increase in the expression of ifn1, mx, interferon regulatory factor 7 (irf7), and pkr genes, followed by upregulation of Mx protein expression." (PMID 29698529, 2018). "To further elucidate the functional role of chicken IRF7 during avian influenza virus (AIV) infection, we generated inducible IRF7 overexpression DF-1 cell lines and performed in vitro infection using low pathogenic AIVs (LPAIVs)." (PMID 30356848, 2018). "pDC:Irf7+ mice had undetectable IFNα/β levels in both the plasma and spleen at all analyzed times post-infection (p.i.)." (PMID 29914621, 2018). "IRF7, an interferon-regulating transcription factor, is an important host gene for the successful defense to IV infections." (PMID 29947965, 2018). "The results indicated that both IRF3 and IRF7 were decreased at early time points but recovered to control levels at 24 h post-GCRV infection." (PMID 28396670, 2017). "Infection of IRF7−/− dams at E6.5 with a s.c. dose of 4 or 6 log10 CCID50 of ZIKVNatal did not result in detectable replicating virus in the placentas or the fetal heads (n = 3 for each dose)." (PMID 28529976, 2017). "Previous studies have shown a role for IRF7 in human metapneumovirus and influenza virus infections." (PMID 27822537, 2016). "We reported that expression of IRF7 was upregulated in nasal epithelial scrapings from human adults after experimental infection with HRV-16." (PMID 26810609, 2016). "Expression of Irf7, which is known to be one of the most inducible Irf genes was induced in the Ifnar1-/- upon infection to an equivalent degree as compared to the WT." (PMID 26918359, 2016). "For example, the roles of IRF3 and IRF7 in innate antiviral immunity against infection of West Nile Virus and dengue virus have been verified in previous studies." (PMID 27449021, 2016).
infection (continued). "In cattle, the antiviral activity of IRF7 and IRF9 has been reported to be associated with both Bovine Herpesvirus1 and Foot-and-Mouth Disease Virus infection." (PMID 27806696, 2016). "Higher expression of IRF7 mRNA in vitro stimulation of PBMCs and in PBMCs from rabbits 3 days post-in vivo infection is suggestive of its involvement in WNV-induced innate immune responses in the rabbit." (PMID 26697438, 2015). "In contrast, infection with H9N2 virus resulted in a robust response of IRF7 in infected DF-1 cells." (PMID 25557928, 2015). "Nod1 (C10) and its responsive genes Irf7 and Stat1 (C11) were elevated late during infection as well as interferon-induced genes Cxcl10, Ifit1-3, Iigp1 and Rsad2 (C7)." (PMID 26367386, 2015). "In these experiments, cervical tissues were treated with either random (r) or IRF7 specific siRNA for 2 days prior to overnight infection with HIV-1." (PMID 26121689, 2015). "As also suggested by the IFN-β neutralization results, disrupting IRF7 gene expression early during infection had little impact on IFN-β synthesis, which implies that IRF7 is not involved early in this immune response." (PMID 25798928, 2015). "Total tissue RNA was isolated before and on days 1 and 3 after infection, and evaluated for IRF7, IFNα, HIV-1 and RelA transcription." (PMID 26121689, 2015). "We again showed that C. muridarum infection was able to induce transcription of IRF7 more substantially at late times during infection." (PMID 25798928, 2015). "Addition of IFN-β neutralizing antibody had a dramatic impact in the down-regulation of IRF7 gene transcription, contrasting the early infection IRF7 results." (PMID 25798928, 2015). "Whereas IRF3 is constitutively expressed at low levels and initiates IFN-I production after viral detection, IRF7 is an ISG that is expressed at high levels in infection and is the master regulator of the IFN-I response." (PMID 26709698, 2015). "Localised productive infection triggered a broad innate response, with type-1 interferon sensitive IRF-7, STAT-1, TRIM5α and ApoBEC3G genes all upregulated during the acute phase but induction did not prevent viral persistence." (PMID 25162725, 2014). "The expressions of RIG-I, IRF-7, and IFNs genes were also assessed in HuH-7 cells following infection." (PMID 24587086, 2014). "In BEAS-2B cells at 10 h of infection, IRF-7, ISG15 and Mx1 expression were significantly down-regulated (p<0.05) while STING expression was significantly up-regulated (p<0.05); expression of IFN-β and IL-6 was unchanged." (PMID 25313647, 2014). "LCMV infection indeed significantly increased the expression of IRF-7 in both adult and infant pDCs but constitutive and post-infection levels remained significantly lower in infant pDCs." (PMID 24376875, 2013). "Others have demonstrated an age-related decrease in IFN response through STAT1, IRF1 and IRF7 signaling following infection with West Nile Virus." (PMID 23936572, 2013). "Though elegant biochemical studies have established that LMP1 activates IRF7, the role of the LMP1/IRF7 pathway during EBV host infection remains to be fully characterized." (PMID 23793113, 2013). "At later times (14–24 h) after infection, IRF7 and TBP are released from the promoter, concomitant with histone H3K9 and H3K14 deacetylation; the attenuation of IFN-A gene transcription." (PMID 22685561, 2012). "The contribution of IRF5 as well as IRF3 and IRF7 activation by IAV during infection and MDP treatment is the subject of ongoing investigation." (PMID 22590599, 2012). "Cellular localization of IRF3 and IRF7 was analyzed by immunofluorescence at different times post-infection." (PMID 22206025, 2011). "TBK-1 is involved in IFN-β production after cytoplasmic recognition of L. monocytogenes, and IRF-7 is increased after infection and promotes an amplification loop of IFN-β production." (PMID 21610853, 2011).
infection (continued). "Only a slight decrease in IRF7 protein was observed 24 hr post-infection, in contrast to the major degradation of IRF3." (PMID 21677781, 2011). "STAT2 binding to the Oas1a promoter in STAT1−/− cells was only significantly enriched at 24 hours post-infection, while Oas1b and IRF7 had significant enrichment at both time points." (PMID 21379341, 2011). "Amastigote numbers were reduced to a similar extent over the first 12h of infection in all cells tested, suggesting an early phase of leishmanicidal activity that was Irf-7-independent." (PMID 20300600, 2010). "Specifically both IFN-α and IFN-β were enhanced in splenocytes derived from Ro52-deficient mice compared with wild-type controls following infection with herpes simplex virus (HSV)-2, strongly suggesting that Ro52 is a negative regulator of IRF7 activity." (PMID 20668674, 2010). "In contrast to what has been observed with other interferon regulatory factor-deficient mice, no obvious structural differences were observed in the organisation and cellular content of the marginal zone in Irf-7−/− mice before or after infection." (PMID 20300600, 2010). "By immunohistochemistry of spleens from infected mice, we showed that MZM and MMM also responded to infection with heightened expression and phagosomal recruitment of IRF-7." (PMID 20300600, 2010). "Reduction in IFN-I production that resulted from IRF3, IRF7, IFNβ or IFNAR deficiency by and large reflected the increase in resistance to lethal infection." (PMID 19325882, 2009). "These include Ifi27, Ifih1, Irf7 and Oas1b which were upregulated at 72 hr and 96 hr post infection except Becn1 that was over-expressed only at 72 hr post infection, and Spn which was over-expressed at all time points." (PMID 18558011, 2008). "In contrast, IRF-3−/− cortical neurons, which had blunted production of IFN, also had markedly lower levels of IRF-7 mRNA after infection." (PMID 17676997, 2007). "The expression of bat IRF7 mRNA was assessed at 0 h, 3 h, 12 h, and 24 h post-infection." (PMID 40108733, 2025). "Thus, during superinfection, and compared to IAV-only infection, Irf7 is reprogrammed from induction to repression, whereas Acads is reprogrammed from repression to induction." (PMID 38446104, 2024). "IRF7 was originally discovered in the context of Epstein–Barr virus (EBV) infection and has since evolved to become a central controller of type I IFNs in response to pathogenic infections." (PMID 38482001, 2024). "Intriguingly, genes such as Ifi204, Irgm1/2, Nos2, Gbp3/7, Usp18, Irf7, Stat1, and Isg15, which were upregulated in response to infection in cells treated with siR_Ctrl, showed decreased upregulation in cells treated with siR_Nostrill following infection." (PMID 39040107, 2024). "Interestingly, we observed that the mRNA levels of IRF7 decreased in DF-1 cells following vvIBDV infection at later time points (≥24 hpi), compared to earlier time points and uninfected controls." (PMID 39872942, 2024). "Our study reveals that IBDV triggers an early IRF7-IFN-β response during infection of DF-1 cells." (PMID 39872942, 2024). "To investigate the impact of IRF7 on viral replication, distribution and spread to specific CNS structures we performed immunohistological analysis (IHC) of different brain regions on day 7 post-infection." (PMID 37737190, 2023). "To clarify how IRFs demonstrate different antiviral effects against human coronavirus infection, we investigate expression levels of antiviral genes in cells transfected with control pcDNA3, IRF1-pcDNA3, IRF3-pcDNA3 or IRF7-pcDNA3 at 24 hours after infection of 229E or OC43." (PMID 37197656, 2023). "In the infection of lymphoid tissues, the majority of IRF7 is expressed in pDC." (PMID 37600806, 2023). "In addition, IRF7 knockdown resulted in an increase in 229E infection at 3 days after infection and OC43 infection at 2 and 3 days after infection." (PMID 37197656, 2023). "IRF3 and IRF7 were also activated from 2 to 5 days after OC43 infection." (PMID 37197656, 2023).